PARP1 (poly(ADP-ribose) polymerase 1)
Diseases named in the same sentence as PARP1 in open-access papers (continued):
Sharing a sentence is not in itself a finding about the gene and the disease.
cancer (continued). "Poly(ADP-ribose) polymerase 1 (PARP1) inhibitors haverevolutionizedthe treatment of many cancers with DNA-repairing deficiencies viasynthetic lethality." (PMID 39292752, 2024). "PARP1/PARP2 inhibitors have emerged as effective drugs for the treatment of cancers with BRCA deficiencies." (PMID 39684238, 2024). "Targeting PARP1 now serves as the basis for the treatment of BRCA-deficient cancer through a mechanism named synthetic lethality." (PMID 39684238, 2024). "Further mechanisms of PARP inhibitor resistance in BRCA-mutated cancer cells include decreased PARP1 trapping by PARP1 mutation and downregulation of PARG, and replication fork stabilization by loss of EZH2 and PTIP." (PMID 38625917, 2024). "By exploiting this synthetic lethality, PARP1 inhibitors (PARPi) can selectively kill HR-deficient cancers such as those that occur in the breast, ovary, prostate and pancreas." (PMID 38580648, 2024). "Inhibition of PARP1 in cancer therapy is a recently adopted strategy to treat cancers where DNA repair is defective, such as HBOC caused predominantly by pathogenic variants in BRCA1 or BRCA2." (PMID 39062754, 2024). "IKKβ is tightly associated with DNA repair in cancer cells, and Parp1-mediated NF-κB signalling governs cell ageing." (PMID 38388665, 2024). "The expression levels of PARP-1 and associated genes are generally higher in various cancers, such as breast cancer, ovarian cancer, endometrial cancer, lung cancer, and prostate cancer, when compared to normal tissues." (PMID 38499384, 2024). "Due to its central role in initiating the DNA damage repair cascade, PARP1 inhibition is significantly more toxic for cancer cells with a deficiency in HR compared to HR-proficient cells." (PMID 39062190, 2024). "Accordingly, PARPis act as “PARP-poisons” because the killing of cancer cells by PARPis completely disappears in PARP1- and PARP2-deficient cells." (PMID 38961202, 2024). "We decided to investigate the status of PARP1 in CML, as PARP1 inhibitors have been approved as treatments for cancer types with deficient DNA repair." (PMID 38704604, 2024). "In summary, our research sheds light on the complex mechanisms underlying PARP inhibitor sensitivity in different genetic contexts and highlights that in BRCA deficient cells, the anti-cancer mechanism is due to loss of PARP1 S-phase activity." (PMID 38521768, 2024). "In these types of cancer, high levels of PARP1 are often associated with low survival rates and more aggressive tumor phenotypes." (PMID 39456202, 2024). "PARP1 pleiotropic functions are implicated in DNA repair, inflammation, and cancer, as well as in mRNA metabolism." (PMID 38247850, 2024). "Third-generation inhibitors were the first to show that PARP1 inhibitors can exert their activity when used alone in BRCA-mutated cancer patients." (PMID 38582911, 2024). "Consistent with our previous findings using several different siRNAs, we also show that XRN2 deficiency in cancer cells hyperactivates PARP1." (PMID 38339346, 2024). "Most PARPis share a similar mode of action that leads to the selective killing of BRCA-deficient cancer cells by targeting PARP1; however, their primary targets and adverse drug reactions vary." (PMID 39007266, 2024). "PARP1 inhibitors are a promising class of drug candidates that target DNA repair deficiencies in cancer cells, especially those with BRCA1/2 mutations." (PMID 39456202, 2024). "Despite PARP1 being widely known for its activities in DNA repair, PARP1 has also been implicated in several other cancer cell functions." (PMID 36941406, 2023). "Studies have reported that ETS expression sensitises cancer cells to PARP-1 inhibition as much as or more than BRCA1/2 deficiency." (PMID 37686260, 2023).
cancer (continued). "Multiple types of cancer cells have been found to express higher levels of PARP-1, and this upregulation has been linked to tumour progression." (PMID 37808196, 2023). "PARP-1 plays a role in DNA damage and repair, and is a well-known target for cancers with BRCA1/2 mutations." (PMID 36814851, 2023). "In 2005, ground-breaking research revealed that BRCA-deficient cancer cells are extremely sensitive to PARP1 inhibitors." (PMID 37508568, 2023). "Through the application of interactomic and proteomic analyses, we found out that Fer associates with the poly [ADP-ribose] polymerase 1 (PARP-1) enzyme in the nucleus of cancer cells and restrains its activity." (PMID 36982326, 2023). "Especially, when there are defects in DNA repair caused by mutations of BRCA1/2, the inhibition of PARP1 results in unrepairable DNA and the apoptosis of cancer cells." (PMID 37215456, 2023). "In combination with the UPLC–HRAM-PRM assay used in this study, the removal of CDEAH adducts from the genome can be analyzed to study the kinetics of the NER and PARP1-dependent BER pathways in various DNA repair-deficient cell lines as well as cancer cells." (PMID 37554969, 2023). "In particular, the knowledge about the roles of PARP1 in DNA repair has led to the development of PARP inhibitors for the treatment of cancers with BRCA mutations." (PMID 37509303, 2023). "BRCA1/2-deficient cancer cells depend on PARP1 for backup DNA repair leading to selective killing of these cancer cells by targeting PARP1." (PMID 37095508, 2023). "ETS transcription factors family members, their associated cancers, and their interaction with PARP-1." (PMID 37686260, 2023). "PARP-1 inhibition has been pursued as a therapeutic choice for cancers deficient in homologous recombination repair (HRR) mechanisms because of its ability to induce synthetic lethality." (PMID 36834491, 2023). "We therefore focused on PARP1, a well-known cancer-associated protein that undergoes PTM (post-translational modification) in many cancer types, for subsequent mechanistic studies." (PMID 37821462, 2023). "PARP1/2 inhibitors (PARPi) are effective clinically used drugs for the treatment of cancers with BRCA deficiencies." (PMID 37844763, 2023). "An increasing amount of studies have now reported that PARP-1 inhibition causes an important increase in DSB DNA damage in cancer cells expressing ETS transcription factors such as Erg, Fli1, or Ets-1." (PMID 37686260, 2023). "Mechanistically, IP-DNQ exterminates NQO1-positive cancer cells by generating excessive reactive oxygen species (ROS), thereby inducing DNA damage, PARP1 hyperactivation, and catastrophic energy loss." (PMID 38136388, 2023). "Inhibition of PARP1/2 activity has become a cornerstone of treatment for advanced cancers with DDR deficiencies and has been extensively studied in the literature." (PMID 37740039, 2023). "PARP1/2 inhibitors are used as an SL therapy for BRCA-mutated cancers, although PARP1 and PARP2 can compensate for the deletion of each other in DNA repair." (PMID 37350942, 2023). "DDR gene alteration creates a reliance on poly(adenosine diphosphate-ribose) polymerase (PARP)-1 for repairing DNA, which causes cancer cell death when PARP-1 is blocked." (PMID 37629155, 2023). "PARP1 inhibitors are effective as monotherapy for BRCA-deficient cancers, whereas they are effective in combination with radiotherapy or other therapeutic modalities for non-gene-deficient cancers." (PMID 38111536, 2023). "A notable example and a poster child of personalised oncology are PARP1/2 inhibitors (PARPi) that selectively kill HR‐deficient (HRD) cancer cells by preventing repair of DNA gaps or single‐strand breaks (SSBs)." (PMID 36929572, 2023).
cancer (continued). "A main part of the changes caused by PARP1-KO affected the synthesis and processing of proteins, cancer development, oxidative phosphorylation, and base excision repair." (PMID 36982223, 2023). "Several PARP1 inhibitors have been FDA-approved for the treatment of DNA damage repair (DDR)-deficient cancers including those harboring BRCA1/2, ATM, and RAD51C mutations." (PMID 37821462, 2023). "These compounds generated oxidative stress in cancer cells, activated the apoptosis pathway, and induced DNA damage, which was associated with the inhibition of PARP1 polymerase activity." (PMID 37175377, 2023). "The loss of PARP1 often leads to impairment in the DNA repair machinery, which can contribute to cancer development." (PMID 35359956, 2022). "PARP1 drives transcription and accelerates base excision repair, and inhibition of PARP1 leads to cell death in cancers deficient in homologous repair by causing defects in the replication fork needed to repair DNA damage." (PMID 36483025, 2022). "A clinically implemented synthetic lethality principle is based on the finding that cancer patients carrying BRCA1/2 mutations are sensitive to inhibition of PARP1." (PMID 36124865, 2022). "Particularly, cancer cells have defects in DNA repair pathways; then, tumor cells are susceptible to PARP-1 inhibition." (PMID 35268667, 2022). "We found that increased susceptibility of cancer cell lines to olaparib correlated with higher mRNA expression levels of 65 proteins that co-occupied stressed replication forks with PARP1." (PMID 36350633, 2022). "PARP inhibitors are typically small-molecule cancer drugs that target PARP1’s catalytic activity, causing entrapment at DNA damage sites and blocking BER." (PMID 36551731, 2022). "Three meta-analyses have consistently shown that the PARP-1 V762A polymorphism is associated with cancer risk in Asian populations." (PMID 36432602, 2022). "PARP-1 suppression enhances the damage of injured DNA resulting in synthetic lethality in DNA-repairing-deficient cancer cells, such as BRCA1/2-deficient cells." (PMID 35956876, 2022). "For example, pioneering studies of SL partners in BRCA1 and BRCA2- deficient cancer cells identified PARP1." (PMID 35055413, 2022). "BRCA1 mutant cancers show minimal resection of DSBs, which renders them deficient in homology-directed repair and sensitive to inhibitors of PARP1." (PMID 35785170, 2022). "PARP1 inhibition (PARPi) in BRCA1/2 mutated tumors has been successful in many types of cancers, including breast, ovarian, prostate, pancreatic, colon, and lung." (PMID 35800362, 2022). "The rational underlying the development of PARP-1 inhibitors is based primarily on the ability of these therapeutics to target cancer cells with a high replication rate and/or a deficiency in DNA repair machinery." (PMID 35158955, 2022). "PARP1/2 inhibitors are at present being used in the clinic to treat cancer patients with BRCA mutations, as additional loss of PARP1 disables functional DNA repair in the cancer cells specifically." (PMID 35380161, 2022). "Cancers which are caused by compromised DNA-repair pathways are extremely sensitive to PARP1 inhibitors." (PMID 35327610, 2022). "Mechanistically, mutations in BRCA1/2 inactivate the HR pathway, and in order to survive, BRCA1/2-mutated cancer cells require the activity of PARP1 in BER and/or a-NHEJ, to prevent the formation of DSBs from unrepaired SSBs during DNA replication." (PMID 36497275, 2022). "Synthetic lethality has emerged as an attractive therapeutic strategy, especially the success of poly (ADP-ribose) polymerase 1 (PARP1)-targeted therapy against the growth of BRCA1/2-mutated cancer cells." (PMID 36180906, 2022).
cancer (continued). "Homologous recombination-deficientBRCA-mutant carcinomas, which rely on PARP1-base excision repairfor survival, are highly sensitive to PARP1 inhibitors through themechanism of synthetic lethality." (PMID 35293552, 2022). "Homologous recombination (HR) repair deficiency impairs the proper maintenance of genomic stability, thus rendering cancer cells vulnerable to loss or inhibition of DNA repair proteins, such as poly(ADP-ribose) polymerase-1 (PARP-1)." (PMID 33487630, 2021). "PARP-inhibitors (PARPi) are a novel drug class that proved to be effective in tumors harboring germline BRCA1/2 (gBRCA) mutations, by inhibiting PARP enzymes and trapping PARP1 on the DNA, ultimately leading to cancer cell death." (PMID 34262869, 2021). "PARP1 inhibitors are used for the treatment of cancers with specific genetic anomalies that make them susceptible to DNA damage in the so-called “chemical synthetic lethality”." (PMID 34207240, 2021). "PARP1 gene expression is also linked to DNA methylation, with important clinical impact in gynaecological malignancies, especially cancers that are BRCA‐mutated." (PMID 34132464, 2021). "Co-occurrence of genetic mutations in tumors with PARP1 alterations involved some genes that were enriched in transcriptional misregulation in cancer pathways (e.g., H3F3A, HIST3H3) and calcium signaling pathways (e.g., ITPKB, RYR2)." (PMID 34531868, 2021). "This treatment modality takes advantage of the dependence of homologous recombination-deficient cancer cells on PARP1 and PARP2 for the repair of endogenous DNA lesions." (PMID 33922595, 2021). "The sensitivity of BRCA mutated cancer cells to PARP1 inhibition has brought this enzyme to the forefront of therapeutic interest, and multiple potent candidate molecules have been and continue to be developed." (PMID 34439854, 2021). "The use of PARP1 inhibitors associated with NPs has been assayed in some cancers such as hepatocellular carcinoma (arsenite and DOX), prostate cancer (nano-olaparib), ovarian cancer (NPs loaded with olaparib and cisplatin) and, especially, breast cancer." (PMID 33923200, 2021). "Since the successful use of the PARP1 inhibitor olaparib in the treatment of cancers caused by BRCA1 and BRCA2 mutations, such as breast, ovarian, pancreatic, and prostate cancers, synthetic lethality-based anticancer therapy has garnered enormous attention." (PMID 34583722, 2021). "Overall, these initial studies suggest that effective PARGi-induced cancer cell targeting requires a cell treatment or cellular genetic background that predisposes to enhanced PARP1/PARP2 activation." (PMID 34806016, 2021). "PARP1 inhibitor has been developed to create synthetic lethality of DNA repair systems in BRCA mutated cancers." (PMID 34207284, 2021). "The aza-steroidal alkylators, ASA-A, ASA-B and ASA-C induced a conspicuously higher increase of the PARP1/ACTB mRNA ratio in the UWB1.289 + BRCA1 than in the BRCA1 mutated UWB1.289 cancer cells." (PMID 34440232, 2021). "Since twelve target genes were associated with neoplasms, data from eight cancer types and over 2,000 patients were scrutinized for co-occurrence or mutual exclusivity of gene amplification, deletion or mutation with PARP1." (PMID 34395585, 2021). "In general, an increased level of PARP-1 expression is considered to be a prognostic marker associated with an aggressive phenotype of malignant tumors and a worse prognosis of patient survival." (PMID 34768872, 2021). "PARP-1 inhibitors have not only been used in BRCA1/2 deficient cancers but also used in combination therapy with DNA-damaging therapeutics to improve their potencies by blocking DNA-repairing process." (PMID 35424391, 2021).
cancer (continued). "High expression of PARP1 is associated with a higher grade of some cancers, including gastric, ovarian, and breast cancers." (PMID 33525741, 2021). "This rationale can also be accounted for the feature of a unique enzymatic event, namely, PARP-1 activation, with PARylation-mediated cellular physiological changes being associated with the development of cancer." (PMID 33805293, 2021). "Several PARP1/2 inhibitors that target HR-deficient types of cancer have already entered the clinic with many more PARPis in various stages of development." (PMID 34572428, 2021). "For example, BRCA mutated cancers that are HR-deficient are vulnerable to inhibition of PARP1-mediated base excision repair and NHEJ – an example of synthetic lethality." (PMID 34277419, 2021). "This unrestrained fork progression by PARP1 inhibition therefore promotes the synthetic lethality observed in homologous recombination deficient cells and cancers." (PMID 34806016, 2021). "Most studies in these cancers have shown that a higher expression of PARP-1 is associated with poor outcomes." (PMID 34830749, 2021). "PARP-1 inhibition has been linked to the better response to therapy in various cancers, including PAC." (PMID 33923200, 2021). "Administration of PARP‐1 inhibitors (rucaparib and olaparib) to patients with high‐risk neuroblastoma can make cancer cells sensitive to X‐rays, and its mechanism of action is likely to be accumulated DNA damage." (PMID 34766149, 2021). "Recent studies have demonstrated that inhibition of PolQ in DSB repair-deficient cancers, as in the case of PARP-1, also results in synthetic lethality." (PMID 34490123, 2021). "PARP-1 has been investigated as a therapeutic oncology target, it induces synthetic lethality efficiently in cancers that are deficient in certain DNA repair mechanisms (BRCA1/2 and ATM) and dependent on upregulated PARP-1 activity for survival." (PMID 34069967, 2021). "Previous studies in other cancer types have reported the efficient targeting of PARP1 in XRCC1 deficient lines." (PMID 34067180, 2021). "Among the 17-member poly(ADP-ribose) polymerase (PARP) enzyme family, PARP1/2 have emerged as the most extensively studied owing to the success of PARP1/2 inhibitors to treat DNA repair-deficient cancers." (PMID 34874266, 2021). "The important message from this development is that therapeutic benefit has been increased more by identifying new susceptible cancer targets for existing PARP1/PARP2 inhibitors than by developing novel, improved inhibitors." (PMID 34210965, 2021). "PARP1 inhibitors (PARPis) have been shown to selectively kill homologous recombination repair (HRR) deficient cancer cells by increasing PARP1-DNA binding due to suppression of autoPARylation of PARP1 on DNA4." (PMID 31992690, 2020). "We demonstrated that aberrant FGFR1 and PARP1 expression was associated with cancer stem cell-like phenotype, regulated DNA repair, and modulated response to therapy in PDAC cells." (PMID 32276472, 2020). "More investigations are encouraged to provide more evidence regarding the role of PARP‐1 rs1136410 C>T polymorphism to the aetiology of cancer predisposition." (PMID 33108038, 2020). "XRCC1 and PARP1 deficient cancer cells have been demonstrated to show greater sensitivity to cisplatin." (PMID 33076245, 2020). "PARP1 inhibitors are used for the treatment of BRCA1-deficient cancers, as inhibition of PARP1 generates more single-strand DNA damage, which results in DSBs and consequently leads to a synthetic lethality with BRCA1 deficiency." (PMID 32591500, 2020). "Poly (ADP-ribose) polymerase-1 (PARP1) enzyme gene products are important proteins associated with cancer risk." (PMID 31983162, 2020). "Another study showed that rs1136410 (i.e. Val762Ala polymorphism) reduces the enzymatic activity of PARP1 through increasing Km, suggesting a possible cancer risk of carriers of rs1136410." (PMID 33284833, 2020).